CHI3L1 (chitinase 3 like 1)
Diseases named in the same sentence as CHI3L1 in open-access papers (continued):
Sharing a sentence is not in itself a finding about the gene and the disease.
melanoma (52 papers, 2007 to 2025). A malignant, usually aggressive tumor composed of atypical, neoplastic melanocytes. "Although elevated serum CHI3L1 levels have been linked to increased mortality in melanoma patients, the primary sources of CHI3L1 are immune cells, such as macrophages and neutrophils, rather than tumor cells themselves." (PMID 40643503, 2025). "Within the melanoma tissue, CHI3L1 originates from the cancer cells and tumor-associated macrophages." (PMID 33920100, 2021). "Our results fit with recent reports, showing that MAPK and AKT pathway activation caused by CHI3L1 promote recovery from oxidant injury and inflammasome activation in melanoma metastasis." (PMID 31561550, 2019). "Melanoma Associated CHI3L1 was also reported to promote immune cell recruitment." (PMID 34612767, 2021). "In melanoma, the main source of CHI3L1 is tumor cells and tumor-associated macrophages." (PMID 33920100, 2021). "In this model, Tg mice in which human CHI3L1 was selectively overexpressed in the lung showed significantly increased lung metastasis of injected melanoma cells compared to wild-type (WT) controls." (PMID 40643503, 2025). "BRP-39 (Chi3l1)-deficient T cells exhibit enhanced Th1 and CTL responses, reducing melanoma lung metastasis by promoting antitumor immunity." (PMID 39795077, 2024). "B16‐F10 melanoma cells were injected into C57BL6/mice followed by intravenous anti‐Chi3L1 antibody at 0.5 mg·kg−1 twice a week for eight weeks." (PMID 34861103, 2022). "It is also noteworthy that CHI3L1 signaling promotes oxidant-induced apoptosis, lung injury, and melanoma metastasis through activation of the AKT pathway." (PMID 36615523, 2022). "CHI3L1 regulates apoptosis, pyroptosis, inflammasome activation, oxidative injury, antimicrobial responses, melanoma metastasis, and TGF-1 development through activation of the MAPK, AKT, and Wnt/-catenin signaling pathways." (PMID 36615523, 2022). "When viewed in combination, these studies demonstrated an essential role of CHI3L1 in melanoma inhibition of T cell co-stimulation and the induction of CTLA-4 and its ligands." (PMID 36618349, 2022). "In an experimental murine melanoma model, T cell-derived CHI3L1 was associated with enhanced lung metastasis and interferon-γ production suggesting also a prominent role of CHI3L1 in melanoma immunotherapy." (PMID 33920100, 2021). "Our data further indicate that the CHI3L1 induced alterations in the supernatants of melanoma cells are related to the competitive displacement of HS-bound molecules." (PMID 33920100, 2021). "The analysis of the melanoma cell secretome indicated that CHI3L1 increases the abundance of various cytokines, such as CC-chemokine ligand 2 (CCL2), and growth factors, such as vascular endothelial growth factor A (VEGF-A)." (PMID 33920100, 2021). "To further understand the role of CHI3L1 in melanoma and for the tumor microenvironment, we analyzed the secretome of human melanoma cells overexpressing CHI3L1." (PMID 33920100, 2021). "Microfluidic experiments indicated that the CHI3L1 altered melanoma cell secretome promoted immune cell recruitment to the vascular endothelium." (PMID 33920100, 2021). "In melanoma, increased CHI3L1 serum levels were shown to correlate with disease severity and poor survival." (PMID 33920100, 2021). "Based on Chi3l1 KO mouse phenotypes in the B16F10 melanoma lung metastasis model, we developed a novel tumor treatment agent based on siRNA and cell-penetrating peptide (CPP) complexes." (PMID 29403003, 2018). "At 14 days from intravenous injection of 5 × 105 B16F10 melanoma cells into WT and Chi3l1 KO mice, metastatic melanoma colonies were observed on the lung surface." (PMID 29403003, 2018). "Deletion of Chi3l1 in T cells in mice show reduced melanoma lung metastasis with increased IFNγ and TNFα-producing T cells in the lung." (PMID 29403003, 2018).
melanoma (continued). "Chi3l1-deficient T cells were differentiated into T cells with Th1-prone phenotypes with hyper-responsive to IFNγ signaling and melanoma lung metastasis was significantly reduced in the mice with both Chi3l1 total knock out and CD4−Cre system." (PMID 29403003, 2018). "Here the authors show that Chi3l1 inhibits the T cell response by negatively regulating their activation and that, in a mouse model of melanoma, T cell-targeted silencing of Chi3l1 results in reduced lung metastasis." (PMID 29403003, 2018). "In these experiments the transgenic overexpression of Chi3l1/YKL-40 in Chi3l1 null mice significantly opposed the ability of Poly(I:C) to inhibit melanoma metastasis." (PMID 27198666, 2016). "Null mutations of TMEM219 or IL-13Rα2 also phenocopied one another as regards the ability of Chi3l1 to inhibit oxidant-induced apoptosis and lung injury, promote melanoma metastasis and stimulate TGF-β1." (PMID 27629921, 2016). "These in vivo studies demonstrated that Chi3l1 expression and production are augmented after the administration of B16 melanoma cells and that Poly(I:C) is a potent inhibitor of these metastasis permitting responses." (PMID 27198666, 2016). "Our demonstration that Type I IFNs mediate their anti-melanoma effects, at least in part, by inhibiting the Sema7a-Chi3l1 pathway raises the interesting possibility that the Sema7a-Chi3l1 axis plays an important role in the immunoediting response." (PMID 27198666, 2016). "Transgenic (Tg) mice overexpressing CHI3L1 that received melanoma cells through tail vein injection developed extensive metastatic melanoma colonies in the lungs." (PMID 26440614, 2015). "Therefore, bispecific antibodies targeting both PD-1/PD-L1 and CHI3L1 represent a promising therapeutic strategy for pulmonary metastasis and melanoma progression." (PMID 40643503, 2025). "Interestingly, CHI3L1 (YKL40) works as an IL13Rα2 ligand that promotes cell signaling in melanoma and other diseases." (PMID 37963919, 2023). "CHI3L1 activates the IL‐13Rα2‐dependent activation of the AKT pathway in melanoma metastasis." (PMID 34758182, 2022). "The levels of circulating CHI3L1 are also increased in cancers of the prostate, colon, lung, rectum, ovary, kidney, breast, glioblastomas and malignant melanoma where they frequently correlate with disease progression and inversely with disease-free interval and survival." (PMID 36618349, 2022). "Further, it was reported that CHI3L1 activates the AKT pathway in melanoma metastasis." (PMID 36615523, 2022). "For example, chitinase-3-like protein 1 (CHI3L1) could bind to IL-13Rα2 and regulate oxidant injury, apoptosis, and melanoma metastasis." (PMID 33450900, 2021). "In the present study, we have shown that CHI3L1 affects the secretome of melanoma cells." (PMID 33920100, 2021). "In the present work, we investigated whether the interaction of CHI3L1 with the extracellular matrix of melanoma cells can trigger an inflammatory activation of endothelial cells." (PMID 33920100, 2021). "However, in line with elevated CCL2 levels, we found increased recruitment of CD45+ leukocytes to endothelial cells, which had been stimulated with a conditioned medium harvested from CHI3L1-treated melanoma cells." (PMID 33920100, 2021). "To elucidate the direct function of Chi3L1 in lung tumor growth in vivo, we next investigated lung tumorigenesis in allograft mice inoculated with B16F10 melanoma transduced by a Chi3L1 short hairpin RNA (shRNA)-expressing adenoviral vector (Chi3L1 shRNA mice)." (PMID 32127023, 2020). "Notably, silencing of Chi3l1 expression in the lung using peptide-siRNA complex efficiently reduced mouse melanoma lung metastasis with enhanced Th1 and CTL responses." (PMID 30165890, 2018). "Melanoma lung metastasis was significantly reduced in the Chi3l1 KO mice compared to WT animals." (PMID 29403003, 2018).
melanoma (continued). "In addition, in vivo siRNA silencing of Chi3l1 with a cell-penetrating peptide dNP2 efficiently inhibited melanoma lung metastasis by increasing both Th1 and cytotoxic T-lymphocyte (CTL) responses." (PMID 29403003, 2018). "Thus, Type I IFNs are induced during and play a critical role in the pathogenesis of the RLH-induced inhibition of Chi3l1 and melanoma metastasis." (PMID 27198666, 2016). "Thus, Poly(I:C) inhibits melanoma metastasis, Chi3l1/BRP-39 accumulation and IL-13Rα2 expression via the RLH innate immune pathway and TLR3 does not play a major role in these responses." (PMID 27198666, 2016). "We hypothesized that interventions that alter the induction of Chi3l1/YKL-40/BRP-39 decrease the metastatic spread of malignant melanoma and other tumors." (PMID 27198666, 2016). "Specifically, they characterize the first receptor for any GH 18 moiety by demonstrating that the chitinase-like protein (CLP) Chi3l1 binds to, signals, and regulates oxidant injury, apoptosis, pyroptosis, inflammasome activation, pathogen responses, melanoma metastasis, and TGF-β1 via IL-13Rα2." (PMID 23972995, 2013). "Moreover, these novel findings are supported by other groups that identified the upregulation of PDPN as lymphatic anchorage marker by CHI3L1 in macrophages, as well as reduction in lymphatic spreading of B16-BL6 melanoma cells upon treatment with anti-CHI3L1 antibodies." (PMID 38605414, 2024). "Since CHI3L1 null mutation or a-CHI3L1 neutralizing antibody treatment reduced metastatic spread, they do not determine if the inhibition of ICOS and ICOSL and or the induction of CTLA-4 are due to the direct effects of CHI3L1 or due to the decreased metastatic spread of melanoma." (PMID 36618349, 2022). "However, despite the importance of tumor associated Chi3l1, interventions that inhibit Chi3l1 have not been adequately described and the ability of these interventions to control the progression of melanoma and other tumors has not been defined." (PMID 27198666, 2016). "Here we demonstrate that CHI3L1 inhibits the expression of ICOS, ICOSL and CD28 while stimulating CTLA-4 and the B7 moieties in melanoma lung metastasis." (PMID 36618349, 2022). "At least additive antitumor effects were seen in the mice with melanoma lung metastasis treated simultaneously with individual antibodies against CTLA-4 and CHI3L1." (PMID 36618349, 2022). "The CHI3L1/IL‐13Rα2 complex accompanied by TMEM219 promotes oxidant‐induced apoptosis, lung injury, and melanoma metastasis through activation of the macrophage ERK/AKT pathway." (PMID 34758182, 2022). "Each anti-CHI3L1 and anti-CTLA-4 antibody inhibited melanoma lung metastasis when compared to isotype controls." (PMID 36618349, 2022). "At least additive antitumor responses were seen in melanoma lung metastasis treated with anti-CTLA-4 and anti-CHI3L1 antibodies in combination." (PMID 36618349, 2022). "CHI3L1 activates the AKT signaling pathway, thereby regulating cancer cell apoptosis and melanoma metastasis." (PMID 36615523, 2022). "Similar to our data from melanoma cell lines, we observed some VEGF targets in the top 65 DEGs, such as CHI3L1, KLF1 and ESM1." (PMID 30242167, 2018). "To confirm the increased tumoricidal activity in Chi3l1 KO CD8 T cells, we performed co-culturing experiments with pre-activated WT or Chi3l1 KO CD8 T cells and B16F10 melanoma cells." (PMID 29403003, 2018). "Here, the authors show that TMEM219 is a IL-13Rα2 co-receptor and modulates oxidant-induced apoptosis and lung injury, melanoma metastasis and TGF-β1 signalling, downstream of Chi3l1-IL-13Rα2." (PMID 27629921, 2016). "To determine if the bispecific antibodies that target CHI3L1 and CTLA-4 particularly effective, we generated bispecific antibodies and their antitumor effects in a T cell-melanoma cell coculture system were evaluated and compared to individual antibodies, alone or in combination." (PMID 36618349, 2022).
melanoma (continued). "Notably, the CHI3L1/IL-13R2 (its receptor) complex and transmembrane protein 219 (TMEM219) exacerbate lung damage, melanoma metastasis, and oxidant-induced apoptosis by activating the AKT pathway." (PMID 36615523, 2022). "Another study elucidated that chitinase 3-like 1 (CHI3L1), an enzymatically inactive mammalian chitinase, interacts with the extracellular matrix of melanoma cells, increasing the secretion of various cytokines, such as CCL2, and growth factors, such as vascular endothelial growth factor A (VEGF-A)." (PMID 34885161, 2021). "We found that migration of Ret melanoma cells was promoted by the CHI3L1 enriched BLM conditioned medium but not by CHI3L1 alone." (PMID 33920100, 2021). "In addition, Poly(I:C) inhibition of tumor-induced Chi3l1 was also dependent on IFNAR1 and the ability of Poly(I:C)-induced RLH activation to inhibit melanoma metastasis was significantly decreased in mice with null mutations of IFNAR1." (PMID 27198666, 2016). "To test this notion, we determined if CHI3L1 inhibits co-stimulation and stimulates the CTLA-4 axis without melanoma metastasis." (PMID 36618349, 2022).
Obesity (51 papers, 2009 to 2025). Accumulation of substantial excess body fat. "Among the three genetic predispositions associated with airway remodeling, PLAUR, and CHI3L1 are potentially linked to obesity." (PMID 38562155, 2024). "It was observed that pro-inflammatory cytokines enhance CHI3L1 expression in adipocytes, suggesting a strong association between CHI3L1 and obesity, as well as obesity-induced pro-inflammatory responses." (PMID 38562155, 2024). "Elevated CHI3L1 levels have been associated with aging, degree of obesity, diabetes, and cardiovascular complications including atherosclerosis, acute myocardial infarction, and coronary artery disease." (PMID 30311184, 2018). "Our results, on the other hand, confirmed an independent, positive association of obesity and age with CHI3L1 levels, which has also been reported in earlier studies." (PMID 30311184, 2018). "Likewise, overexpression of CHI3L1 induced obesity and increased allergic airway inflammation in association with high-fat diet." (PMID 26783384, 2015). "Intriguingly, beyond the chronic inflammations delineated in Section 2.1, emerging evidence indicates the modulation of cardiovascular diseases, liver injuries, kidney diseases, systemic musculoskeletal disorders, and obesity by CHI3L1." (PMID 38667293, 2024). "We also found that obesity (p = 0.006) and CC (p = 0.012) increased plasma levels of chitinase 3-like 1 (YKL-40), a marker that contributes to chronic inflammation and oncogenic transformation." (PMID 34445187, 2021). "The results of this study indicate that effects of PAP treatment on CHI3L1 levels depend on the level of obesity (measured by BMI) in a population of patients with moderate to severe OSA." (PMID 30311184, 2018). "When assesing the role of PAP treatment and obesity on CHI3L1 levels, our results came to similar conclusions with these studies." (PMID 30311184, 2018). "The aim of this preliminary study was to evaluate the roles and interaction of OSA severity (AHI, oxygen desaturation index [ODI]), and obesity (BMI) on CHI3L1 levels and CHIT1 activity in a clinical cohort of patients with moderate to severe OSA (AHI ≥ 15)." (PMID 30311184, 2018). "For instance, Chi3l1 (YKL-40, chitinase 3-like 1) has recently been shown to represent an obesity-independent novel marker of type 2 diabetes." (PMID 22369239, 2012). "In obesity-associated T2DM patients, both circulating and visceral adipose tissue expression levels of Chi3l1 significantly increase, whereas upregulated Chi3l1 levels can be decreased through weight loss resulting from a conventional hypocaloric diet but not gastric bypass surgery." (PMID 39769202, 2024). "Additionally, CHI3L1 may be associated with insulin resistance and obesity in the pathogenesis of NASH, and hepatic insulin sensitivity can be partially restored by parenteral given anti-Chi3L1 monotherapy." (PMID 38962736, 2024). "Association between OSA severity and CHI3L1 levels/CHIT1 activity (independent of or dependent on obesity) could not be confirmed." (PMID 30311184, 2018). "Obesity and age were independently associated with CHI3L1 levels but not with CHIT1 acitvity." (PMID 30311184, 2018). "Association between OSA severity and CHI3L1 levels or CHIT1 activity (independent of or dependent on obesity level) could not be confirmed." (PMID 30311184, 2018). "Chitinase-3-like protein-1 (CHI3L1), also known as YKL-40 or human cartilage glucoprotein-39, is a member of mammalian chitinase-like proteins with increased gene expression levels in obesity and T2D." (PMID 24829560, 2014). "Furthermore, individuals with obesity showed significantly higher plasma CHI3L1 concentrations compared to their non-obese counterparts." (PMID 38562155, 2024).
Obesity (continued). "Further investigation by single cell RNAseq identified four functional molecular endotypes including obesity specific subsets defined by an inflammatory endotype related to immune cell regulation, fibroblast activation and inflammatory signaling, with up‐regulated CXCL12, CFD and CHI3L1 expression." (PMID 37006170, 2023). "In underexpressed genes, obesity did not affect PI3, CHI3L1, and IL-8 and significantly reduced CPA3 expression." (PMID 37445432, 2023). "The effect of OSA severity on CHI3L1 levels, with and without the degree of obesity, was not significant indicating that the AHI and ODI as markers of OSA severity may not be appropriate to assess the impact of OSA on CHI3L1 levels in the same patient populations." (PMID 30311184, 2018).